S100A2 (S100 calcium binding protein A2)
Description:
May function as calcium sensor and modulator, contributing to cellular calcium signaling. May function by interacting with other proteins, such as TPR-containing proteins, and indirectly play a role in many physiological processes. May also play a role in suppressing tumor cell growth.
Synonyms: S100L; CAN19
Tractability: Antibody: the Human Protein Atlas places it where antibodies can reach. PROTAC: ubiquitination databases record sites on it.
Gene: Protein-coding gene on chromosome 1 (153,560,950 to 153,568,674, reverse strand). Ensembl gene ENSG00000196754.
Subcellular location (Human Protein Atlas): Cytosol; Nucleoplasm; Nucleoli; Plasma membrane
Gene Ontology:
Molecular function: identical protein binding; protein binding; calcium ion binding; calcium-dependent protein binding; transition metal ion binding
Biological process: endothelial cell migration
Genetic constraint (gnomAD): Loss-of-function variants: 6 observed, 5.8 expected, observed/expected ratio (o/e) 1.03, 90% interval 0.56 to 1.8. That is too few expected variants to judge how well the gene tolerates losing a copy. Missense variants: 103 observed, 121.44 expected, observed/expected ratio (o/e) 0.85, 90% interval 0.72 to 1. Synonymous variants: 44 observed, 48.64 expected, observed/expected ratio (o/e) 0.9, 90% interval 0.71 to 1.16.
Homologues: Orthologues: chimpanzee S100A2 (99% identical), macaque S100A2 (98% identical), pig S100A2 (90% identical), dog S100A2 (85% identical), mouse S100a2 (45% identical), zebrafish s100s (43% identical), zebrafish s100t (43% identical), zebrafish s100a10a (29% identical), tropical clawed frog s100a11 (26% identical). Paralogues in human: S100A4 (60% identical), S100A1 (48% identical), S100A5 (47% identical), S100A6 (45% identical), S100A3 (41% identical), S100B (40% identical), S100Z (40% identical), S100P (39% identical), S100A10 (33% identical), S100A12 (33% identical), S100A9 (32% identical), S100A13 (31% identical), and 9 more.
Diseases named in the same sentence as S100A2 in open-access papers:
S100A2 is named in the same sentence as 122 diseases in open-access papers, as found by Europe PMC text mining. Sharing a sentence is not in itself a finding about the gene and the disease. The quoted sentences say what the papers report.
pancreatic cancer (29 papers, 2009 to 2025). "S100A2 is associated with immunological phenotypes in the tumor microenvironment of pancreatic cancer." (PMID 35885660, 2022). "Based on the high expression of S100As members in pancreatic cancer, the association between mRNA expression of S100A2/4/6/10/14/16 and prognosis of pancreatic cancer patients were further analyzed." (PMID 34530774, 2021). "Previously, it has been demonstrated that S100A2 upregulation in pancreatic cancer is associated with tumor invasion and poor prognosis." (PMID 34485257, 2021). "Loss of nuclear S100A2 has been reported in multiple cancers including early stage oral cancer, pancreatic cancer, non-small cell lung carcinoma and our findings of nuclear loss of S100A2 support these studies." (PMID 25591983, 2015). "On the other hand, a high expression of S100A2 was associated with a poorer prognosis in patients with nonsmall-cell lung cancer, hepatocellular carcinoma, ovarian cancer, endometrial carcinoma, pancreatic cancer, prostate cancer, oral squamous cell carcinoma, colorectal cancer, cholangiocarcinoma." (PMID 35885660, 2022). "Fourth, although previous studies reported a similar efficacy of S100A2 in patients who received adjuvant chemotherapy, it has recently been shown that increased S100A2 expression is associated with squamous and basal-type pancreatic cancers with poor prognosis." (PMID 38316853, 2024). "However, the molecular mechanism underlying S100A2 in pancreatic cancer remains to be analyzed." (PMID 37758734, 2023). "The knockdown of S100A2 significantly reduced the motility of pancreatic cancer cell lines in both wound healing and transwell migration assays." (PMID 40092486, 2025). "These two cell lines had the highest baseline expression of S100A2 among four metastatic pancreatic cancer cell lines." (PMID 40092486, 2025). "Consistent with prior literature, we observed significantly elevated levels of RAGE ligands—HMGB1, S100A2, and S100P—in both human and murine pancreatic cancer cell lines relative to normal pancreatic tissue." (PMID 39796649, 2024). "To test this, we stimulated cells with RAGE ligands observed to be upregulated in human pancreatic cancer, including S100P, S100A2, and HMGB1." (PMID 39796649, 2024). "Even within a specific type of cancer, such as pancreatic cancer, both tumor suppressor and promoter effects of S100A2 have been observed." (PMID 37627239, 2023). "To understand the possible effects of S100A2 on PDAC, we analyzed the expression of S100A2 in human pancreatic cancer cells PANC-1, BxPC-3, Patu8988, SW1990, CFPAC-1, and HPNE." (PMID 37758734, 2023). "We studied the increase in S100A2 expression by analyzing the Oncomine dataset and pancreatic cancer tissues." (PMID 37758734, 2023). "In one study, high levels of S100A2 in pancreatic tumors were found to correlate with cancer progression and poor prognosis of patients." (PMID 37627239, 2023). "Another study indicated that the high expression of S100A2 is an independent prognostic marker for the poor prognosis of pancreatic cancer." (PMID 35432485, 2022). "As a mechanism of downregulating S100A2, the promoter methylation of S100A2 is involved in the development of pancreatic cancer in vitro." (PMID 35885660, 2022). "We first analyzed the expression of S100A2/4/6/10/14/16 in human pancreatic cancer lines (PANC-1, CFAPC-1, MIA PaCa-2 and ASPC-1), and human pancreatic cell line hTERT-HPNE served as control by real-time PCR." (PMID 34530774, 2021).
pancreatic cancer (continued). "Further studies consist of larger sample sizes (more clinical samples and different pancreatic cancer cell lines) are required to validate the findings above and to explore the clinical application of S100A2/4/6/10/14/16 in the treatment of PDAC." (PMID 34530774, 2021). "We then tested the expression of S100A2/4/6/10/14/16 in pancreatic cancer tissues, which were from three PDAC patients undergoing surgery." (PMID 34530774, 2021). "According to the signaling pathway activated by S100A2/RAGE in pancreatic cancer cells, S100A2 can be used as either a tumor suppressor or a tumor promoter." (PMID 34804125, 2021). "After finding that the transcriptional level of S100A2/4/6/10/14/16 was highly expressed in pancreatic cancer, we further analyzed the expression of S100A2/4/6/10/14/16 with tumor stage for pancreatic cancer using GEPIA2 and Linkedomics database." (PMID 34530774, 2021). "Nine S100s members, including S100A2/A4/A6/A10/A11/A13/A14/A16/P were significantly upregulated in pancreatic cancer (fold change = 2, p < 0.001)." (PMID 34804125, 2021). "Real-time PCR was used to detect the expressions of S100A2/4/6/10/14/16 in four pancreatic cancer cell lines and pancreatic cancer tissues from PDAC patients undergoing surgery." (PMID 34530774, 2021). "S100A2 is also reported to be a potential marker of tumor progression or prognosis in pancreatic carcinogenesis and pancreatic cancer." (PMID 33750880, 2021). "From the results, we noted high expression of S100A2/4/6/10/14/16 in the pancreatic cancer tissue of patient one." (PMID 34530774, 2021). "In our study, we indicated that the expression of S100A2 in pancreatic cancer tissues was higher than that in normal pancreatic tissues." (PMID 34530774, 2021). "Overexpression of S100A2 was related to advanced histological grade, high T stage, and poor prognosis in pancreatic cancer." (PMID 34804125, 2021). "In Pei’s dataset, the mRNA expression level of S100A2 was overexpressed in pancreatic carcinoma versus normal samples with a fold change of 7.68." (PMID 34804125, 2021). "S100A2, for example, is overexpressed in pancreatic cancer tissue and seems to be a good predictor regarding the response to pancreatectomy of pancreatic cancer patients." (PMID 32722137, 2020). "Several of these S100A genes such as S100A2, A4 and A6 have been shown to be involved in pancreatic cancer." (PMID 25072505, 2014). "In addition, overexpression of S100A2 in KPC1199, a mouse pancreatic cancer cell line, caused a larger tumor burden determined by bioluminescence imaging in a hemi-spleen injection model of liver metastasis." (PMID 40092486, 2025). "Moreover, overexpression of S100A2 in KPC1199, a mouse pancreatic cancer cell line, caused a larger tumor burden in a hemi-spleen injection model of liver metastasis." (PMID 40092486, 2025). "In addition to RAGE expression, the expression of the RAGE ligands HMGB1, S100A2, and S100P was significantly upregulated in both human and murine pancreatic cancer cell lines when compared to normal pancreas." (PMID 39796649, 2024). "have described how S100A2 could be involved in the pathogenesis of pancreatic cancer and that it is correlated with the metastasis of pancreatic cancer." (PMID 38316853, 2024). "This means that S100A2 protein expression could predict the benefit of adjuvant treatment in patients with resected pancreatic cancer." (PMID 38316853, 2024). "Using data from pancreatic cancer patient samples from The Cancer Genome Atlas (TCGA), we demonstrated that although there was no change in the expression of RAGE, the RAGE ligands, S100P and S100A2, were significantly increased in pancreatic tumors when compared to normal pancreatic tissue." (PMID 39796649, 2024).
pancreatic cancer (continued). "Studies in pancreatic cancer have demonstrated that S100A2 could be used as a prognostic marker to identify patients who are more responsive to immunotherapy." (PMID 37476187, 2023). "However, the relationship between S100A families and proliferation or apoptosis of HCC( Over-expression of S100A2 in pancreatic cancer correlates with progression and poor prognosis." (PMID 37420211, 2023). "In this study, we found S100A2 knockdown could inhibit the malignant biological behavior of pancreatic cancer cells by increasing the ubiquitination of β-catenin." (PMID 37359528, 2023). "Altogether, S100A2 can promote pancreatic cancer cell metastasis and EMT in vivo and in vitro." (PMID 37758734, 2023). "These conflicting reports clearly suggest that the role of S100A2 in pancreatic cancer is complex and appears to be dependent on yet unknown molecular characteristics of individual tumors." (PMID 37627239, 2023). "However, in a different study, high levels of S100A2 correlated with high overall survival in pancreatic cancer patients treated with adjuvant therapy." (PMID 37627239, 2023). "Next, we knocked down of S100A2 in PANC-1 cells to explore the role of S100A2 in pancreatic cancer." (PMID 37359528, 2023). "Moreover, we found that S100A2 is a novel regulatory factor for pancreatic cancer cell metastasis, with SMAD4 being a potential downstream target, and together they form the S100A2/SMAD4 axis to promote cellular invasion and migration." (PMID 37758734, 2023). "S100A2 is an unfavorable prognostic indicator in pancreatic cancer, and S100A2 expression is positively correlated with the expression of programmed cell death 1-ligand 1 (PD-L1) in pancreatic cancer cells in vivo." (PMID 35885660, 2022). "A large retrospective study suggests that S100A2 may have the potential to become a biomarker for predicting pancreatectomy or replication therapy in patients with pancreatic cancer." (PMID 34804125, 2021). "S100A2/4/6/10/14/16 were altered in 55 samples of 177 patients with pancreatic cancer (31%)." (PMID 34530774, 2021). "On this basis, we hypothesized that the co-expression of S100A2 and PD-L1 in pancreatic cancer might be based on the activation of the S100A2-Akt-PD-L1 signaling pathway." (PMID 34887861, 2021). "The current research results indicate that the increased expression of S100A2/4/6/10/14/16 in PDAC tissue may play an important role in the occurrence of pancreatic cancer." (PMID 34530774, 2021). "S100A2, which involves a number of cellular processes such as cell cycle progression and differentiation, was dysregulated in lung, gastric, esophageal, ovarian, bladder, breast, thyroid, melanoma and pancreatic cancer." (PMID 34727106, 2021). "However, several later studies have shown overexpression of S100A2 in other cancers including non-small cell lung cancer, esophageal, ovarian, bladder, breast, thyroid, melanoma and pancreatic cancer." (PMID 25591983, 2015). "Moreover, LOX was 1 out of only 5 probe sets that overlapped between the Glasgow cohort and the Collisson signatures of poor prognosis in pancreatic cancer (the others being S100A2, TWIST, NT5E and PAPPA)." (PMID 26077591, 2015). "S100A2 protein levels in a pancreatic cancer cohort of 115 patients were measured by IHC." (PMID 19399185, 2009). "However, the effect of S100A2 on pancreatic cancer has rarely been reported." (PMID 37758734, 2023). "High S100A2 expression is associated with an unfavorable clinical course in brain tumors, such as low-grade glioma and glioblastoma, NSCLC, hepatocellular carcinoma, ovarian cancer, endometrial carcinoma, pancreatic cancer, prostate cancer, colorectal cancer, and cholangiocarcinoma." (PMID 35885660, 2022). "However, the prognostic role of S100A2 in pancreatic cancer remains to be studied." (PMID 34530774, 2021). "However, the biological role of S100A2 protein in pancreatic cancer remains unclear." (PMID 38316853, 2024).
pancreatic cancer (continued). "In the present study, the inhibition of SMAD4 rescued the S100A2-enhanced metastasis and EMT of pancreatic cancer cells." (PMID 37758734, 2023). "This study provides evidence for the involvement of TGF-β1 in S100A2-mediated cell metastasis and EMT during the development of pancreatic cancer." (PMID 37758734, 2023). "Like S100A2, S100A11 is described to function as either a tumor suppressor, such as in bladder cancer, or a tumor promoter, such as in pancreatic cancer." (PMID 37627239, 2023). "We found that S100A2 affects cell metastasis and EMT in pancreatic cancer by regulating SMAD4 via the TGF-β/Smad pathway." (PMID 37758734, 2023). "Since gene mutation is an important factor affecting its expression, we further analyzed the genetic alteration in S100A2/4/6/10/14/16 and their correlation with OS and PFS in patients with pancreatic cancer by using cBioPortal online tool." (PMID 34530774, 2021). "Subsequently, the significantly high expression of S100A2 in tumor cells was confirmed by qRT-PCR in pancreatic normal cell line (HPNE) and pancreatic cancer cell lines (AsPC-1, BxPC-3, Capan-1, CFPAC-1, MIA PaCa-2, PATU 8988, PANC-1, SW1990, and T3M4)." (PMID 34887861, 2021). "Altogether, SMAD4 regulated S100A2 function in EMT and the metastasis of pancreatic cancer cells." (PMID 37758734, 2023). "First, although high mRNA expressions of S100A2/4/6/10/14/16 were independent prognostic factors for shorter OS of pancreatic cancer patients, the online databases used in this study lacked proteome-level data." (PMID 34530774, 2021). "S100A2/A10 have recently been suggested as negative prognostic biomarkers for pancreatic cancer." (PMID 34804125, 2021). "Similar observations were made for S100A2 as a negative prognostic biomarker in pancreatic cancer." (PMID 27709523, 2016). "For instance, previous studies reported that S100A2 and S100A10 were the negative biomarker for pancreatic cancer (PC), while S100A4 was profoundly involved in the chemoresistance and survival in are negative prognostic biomarkers in PC cells." (PMID 37420211, 2023).